SCT (secretin)
Diseases named in the same sentence as SCT in open-access papers (continued):
Sharing a sentence is not in itself a finding about the gene and the disease.
SCT also shares sentences with these, for which no sentence is quoted: Diabetes (3 papers); Hypoglycemia (2); Abdominal obesity (1); adenocarcinoma (1); alcoholic cirrhosis (1); angina (1); bile duct cancer (1); bile duct disease (1); breast carcinoma (1); carcinoids (1); cholangiocarcinoma (1); cholangitis (1); cholestasis (1); dyspepsia (1); esophagitis (1); essential hypertension (1); Glycosuria (1); Hypercalcemia (1); inflammation (1); Insulin resistance (1); insulinoma (1); leptospirosis (1); narcolepsy (1); preeclampsia (1); primary sclerosing cholangitis (1); prostate carcinoma (1); pulmonary hypertension (1); rheumatoid arthritis (1); social phobia (1); sphincter of Oddi dysfunction (1).
A further 2 diseases each share a sentence with SCT in 1 paper.